PPP1R3F (protein phosphatase 1 regulatory subunit 3F)
Description:
Glycogen-targeting subunit for protein phosphatase 1 (PP1).
Synonyms: R3F; Hb2E; LL0XNC01-7P3.1
Tractability: Antibody: UniProt predicts a signal peptide or a membrane-spanning region. PROTAC: its protein half-life has been measured.
Gene: Protein-coding gene on chromosome X (49,269,793 to 49,301,461, forward strand). Ensembl gene ENSG00000049769.
Subcellular location: Membrane
Subcellular location (Human Protein Atlas): Nucleoplasm; Vesicles
Gene Ontology:
Molecular function: glycogen binding; protein phosphatase binding; protein phosphatase 1 binding
Biological process: regulation of glycogen (starch) synthase activity; regulation of glycogen biosynthetic process
Cellular component: membrane; protein phosphatase type 1 complex
Homologues: Orthologues: chimpanzee PPP1R3F (99% identical), macaque PPP1R3F (97% identical), dog PPP1R3F (89% identical), pig PPP1R3F (85% identical), rat Ppp1r3f (83% identical), mouse Ppp1r3f (82% identical), guinea pig PPP1R3F (74% identical), Caenorhabditis elegans H18N23.2 (7% identical), Drosophila melanogaster Gbs-70E (6% identical). Paralogues in human: PPP1R3A (20% identical), PPP1R3E (9% identical), PPP1R3D (9% identical), PPP1R3B (9% identical), PPP1R3G (9% identical), PPP1R3C (7% identical).
Diseases named in the same sentence as PPP1R3F in open-access papers:
PPP1R3F is named in the same sentence as 6 diseases in open-access papers, as found by Europe PMC text mining. Sharing a sentence is not in itself a finding about the gene and the disease. The quoted sentences say what the papers report.
colorectal cancer (2 papers, 2021 to 2024). A primary or metastatic malignant neoplasm that affects the colon or rectum. "PPP1R3F encodes one of the protein–phosphatase-1 catalytic subunits involved in glycogen meta-bolism, which has previously been associated with colorectal cancer." (PMID 39000267, 2024). "In addition, hypermethylation of PPP1R3F has been associated with colorectal cancer risk, and rs5953283 PPP1R3F polymorphism has been linked to asthma." (PMID 39000267, 2024). "Our results showed that the methylation of FAM156B, PPP1R3F, and PIH1D3 genes in blood leukocytes is significantly associated with colorectal cancer (CRC) risk and may be potential biomarkers for CRC risk." (PMID 34145793, 2021).
cancer (2 papers, 2021 to 2024). A tumor composed of atypical neoplastic, often pleomorphic cells that invade other tissues. "Studies have observed the abnormal accumulation of glycogen in tumor cell lines, indicating the possible association between PPP1R3F and cancer risk." (PMID 34145793, 2021). "To date, the research about the associations between FAM156B, PIH1D3, and PPP1R3F and cancer mainly focus on the gene expression and conducted on tumor tissue and cell lines, the relationship between methylation of FAM156B, PIH1D3, and PPP1R3F and cancer risk and prognosis is still unclear." (PMID 34145793, 2021). "The present candidate gene study focuses on the role of two X-linked genes, FOXP3 (Forkhead Box P3) and the PPP1R3F (Protein Phosphatase 1 Regulatory Subunit 3F), in PTC predisposition based on a priori biological hypothesis due to the described role of the selected genes in cancer predisposition." (PMID 39000267, 2024).
PPP1R3F also shares sentences with these, for which no sentence is quoted: autism (1 paper); autism spectrum disorder (1); oral squamous cell carcinomas (1); tumor (1).